RN7SKP128 (RN7SK pseudogene 128)
Gene: Miscellaneous RNA gene on chromosome 9 (117,197,118 to 117,197,420, forward strand). Ensembl gene ENSG00000201140.
Homologues: Orthologues: chimpanzee 7SK (90% identical). Paralogues in human: RN7SKP180 (76% identical), RN7SKP9 (76% identical), RN7SKP95 (76% identical), 7SK (75% identical), RN7SKP133 (75% identical), RN7SKP273 (75% identical), RN7SKP171 (75% identical), RN7SKP204 (75% identical), RN7SKP217 (75% identical), RN7SKP79 (75% identical), RN7SKP255 (74% identical), RN7SKP71 (74% identical), and 284 more.